EGFR (epidermal growth factor receptor)
Diseases named in the same sentence as EGFR in open-access papers (continued):
Sharing a sentence is not in itself a finding about the gene and the disease.
head and neck squamous cell carcinoma (continued). "Limited studies are available on EGFR-TK mutations in the head and neck squamous cell carcinoma (HNSCC) globally." (PMID 33968826, 2021). "For example, over-expression of epidermal growth factor receptor (EGFR) has been associated with poor prognosis in head and neck squamous cell carcinoma (HNSCC)." (PMID 27650546, 2016). "Head and neck squamous cell carcinoma (HNSCC) with aberrant epidermal growthfactor receptor (EGFR) signaling is often associated with a poor prognosis and a lowsurvival rate." (PMID 27510965, 2016). "Overexpression of the epidermal growth factor (EGF) receptor (EGFR) is associated with enhanced invasion and metastasis in head and neck squamous cell carcinoma (HNSCC)." (PMID 25797258, 2015). "Due to the association of overexpressed EGFR with poor prognosis of head and neck squamous cell carcinoma (HNSCC), cetuximab, a monoclonal antibody targeting the receptor, is applied in common therapeutic strategies." (PMID 22548923, 2012). "Recent studies have shown that the over expression of epidermal growth factor receptor (EGFR) is associated with a poor prognosis in patients with head and neck squamous cell carcinoma (HNSCC)." (PMID 22994622, 2012). "Head and neck squamous cell carcinoma (HNSCC) exhibits limited response to EGFR blockade with cetuximab, largely due to constant activation of the PI3K/AKT/mTOR pathways." (PMID 42183362, 2026). "Most head and neck squamous cell carcinomas overexpress EGFR, and cetuximab remains the primary targeted agent used in combination with radiotherapy or chemotherapy." (PMID 41010962, 2025). "On the other hand, deguelin performed well in enhancing the apoptosis inducing activity of EGFR tyrosine kinase inhibitor AG1478 on mutant head and neck squamous cell carcinoma." (PMID 40672375, 2025). "Anti-EGFR therapy in head and neck squamous cell carcinoma can initiate adaptive immune response by promoting NK cells mediated significantly higher HLA-DR expression on DC to present tumor antigens to CD8+T cells." (PMID 39820491, 2025). "Another study aimed to evaluate the potential of GPNMB and VEGF as fluorescent imaging targets in primary head and neck squamous cell carcinoma and lymph node metastases, and compare them with epidermal growth factor receptor." (PMID 41180454, 2025). "Clinical validation targeting the epidermal growth factor receptor (EGFR) is particularly notable in head and neck squamous cell carcinoma (HNSCC)." (PMID 40430568, 2025). "Cetuximab (Cet), a monoclonal antibody targeting the epidermal growth factor (EGF) receptor (EGFR), is the first molecularly targeted drug approved for use in advanced head and neck squamous cell carcinoma (HNSCC)." (PMID 40735032, 2025). "PI3K/AKT pathway inhibitors combined with EGFR-targeting drugs have been proposed for the treatment of head and neck squamous cell carcinoma." (PMID 40391080, 2025). "The potential for human safety and the therapeutic efficacy of NIR‐PIT targeting the epidermal growth factor receptor (EGFR) has been reported in patients with head and neck squamous cell carcinoma." (PMID 38888415, 2024). "In head and neck squamous cell carcinomas (HNSCCs), EGFR and PI3K are each known to mediate resistance to inhibition of the other." (PMID 38992135, 2024). "In the nucleus, it stimulates cell cycle progression by increasing the binding of EGFR to PCNA on squamous cell carcinoma of the head and neck (SCCHN) cancer cells." (PMID 38256018, 2024). "EGFR activation leading to the EMT was associated with a metastatic phenotype and reduced sensitivity of head and neck squamous cell carcinoma (HNSCC) cells to cetuximab treatment." (PMID 39309430, 2024). "Dysregulated Epiregulin (EREG) can activate epidermal growth factor receptor (EGFR) and promote tumor progression in head and neck squamous cell carcinoma (HNSCC)." (PMID 38945975, 2024).
head and neck squamous cell carcinoma (continued). "Drugs targeting the Epidermal growth factor receptor signaling pathway, such as cetuximab, have been applied in the treatment of head and neck squamous cell carcinoma (HNSCC)." (PMID 36737832, 2023). "Cetuximab is an agent targeting EGFR and is currently approved for use in head and neck squamous cell carcinoma (HNSCC) and metastatic colorectal cancer; its combination with radiotherapy continues to be studied." (PMID 37542324, 2023). "Liarozole down-regulates transforming growth factor (TGF)-α and EGFR levels in head and neck squamous cell carcinoma." (PMID 37816585, 2023). "Targeting EGFR through monoclonal antibodies has shown positive outcomes, particularly in patients with recurrent or metastatic head and neck squamous cell carcinoma when other treatments have proven ineffective." (PMID 37370896, 2023). "Studies on head and neck squamous cell carcinoma (HNSCC) demonstrated that overexpression of epidermal growth factor receptor (EGFR) increases radio‐resistance." (PMID 37042307, 2023). "Among the main targets, epidermal growth factor receptor (EGFR) is overexpressed in 80%–100% of head and neck squamous cell carcinomas." (PMID 38239635, 2023). "Cetuximab, a chimeric anti-EGFR IgG1 monoclonal antibody, is currently an effective agent for the targeted therapy against head and neck squamous cell carcinoma (HNSCC) and colorectal cancer (CRC) in clinical therapeutics." (PMID 37438719, 2023). "This evaluation supports its use in combination with targeted therapies, e.g., with cetuximab (an anti-EGFR antibody) in squamous cell carcinoma of the head and neck (HNSCC), whereas a 30% objective response rate (ORRs) was observed." (PMID 36829496, 2023). "Cetuximab is a chimeric monoclonal antibody, one of the first anti-EGFR antibodies to be developed, and has been approved for the treatment of colorectal and head and neck squamous cell carcinoma." (PMID 37438719, 2023). "Currently, the EGFR monoclonal antibody cetuximab is generally administrated in combination with radiation for patients with HPV-negative head and neck squamous cell carcinoma." (PMID 35653344, 2022). "The EGFR was chosen as the target due to its over-expression in over 90% of head and neck squamous cell carcinomas (HNSCC)." (PMID 35808089, 2022). "Also, HER3 signaling has been linked to resistance to TKIs targeting the EGFR in head and neck squamous cell carcinoma (HNSCC)." (PMID 36271429, 2022). "Advanced head and neck squamous cell carcinoma (HNSCC) hold a poor prognosis and tumor progression is associated with overexpression of EGFR." (PMID 34596822, 2022). "EGFR-targeting was also applied in the case of head-and-neck squamous cell carcinoma A431 (HNSCC) cell culture, but the type of MF used for mechanical lysis was different." (PMID 36232435, 2022). "The expression of EGFR was increased in drug-resistant head and neck squamous cell carcinoma (HNSCC), resulting in increased IKKβ expression and activation of the downstream NF-κB signaling pathway." (PMID 36313710, 2022). "Over 90% of head and neck squamous cell carcinoma (HNSCC) overexpresses the epidermal growth factor receptor (EGFR)." (PMID 35453686, 2022). "This study aims to evaluate the prognostic significance of a four-gene inflammatory signature in recurrent/metastatic (R/M) head and neck squamous cell carcinoma (HNSCC) patients treated with the EGFR inhibitor cetuximab plus chemotherapy." (PMID 36231138, 2022). "The epidermal growth factor receptor (EGFR) is overexpressed in the majority of head and neck squamous cell carcinomas (HNSCC)." (PMID 36551613, 2022). "Squamous cell carcinoma of head and neck (SCCHN) is a group of cancer that usually overexpresses EGFR molecules." (PMID 35517713, 2022). "Cetuximab is the sole anti-EGFR monoclonal antibody that is FDA approved to treat head and neck squamous cell carcinoma (HNSCC)." (PMID 35011716, 2022).
head and neck squamous cell carcinoma (continued). "EGFR is a receptor tyrosine kinase upstream of the PI3K–Akt–mTOR pathway in head and neck squamous cell carcinomas." (PMID 34067437, 2021). "Again, head and neck squamous cell carcinoma (HNSCC)-derived cells grown in 3D showed decreased sensitivity to either the alkylating agent cisplatin or the EGFR-targeted drug cetuximab." (PMID 33562840, 2021). "Epidermal growth factor receptors (EGFR) are overexpressed on many head and neck squamous cell carcinoma (HNSCC)." (PMID 34383182, 2021). "Wang showed that HA mediated the formation of a complex including CD44 and the epidermal growth factor receptor (EGFR) played major roles in chemoresistance in head and neck squamous cell carcinoma (HNSCC)." (PMID 35154001, 2021). "Conjugates of EGFR-targeting monoclonal antibodies with IRDye700DX are currently being evaluated in a clinical setting for treatment of head-and-neck squamous cell carcinoma." (PMID 33498707, 2021). "A recent study in head and neck squamous cell carcinomas highlighted that genomic aberrations including EGFR amplifications, AKT1 amplifications and CSMD1 deletions, but not PIK3CA, were highly associated with responsiveness to PI3K-targeted drugs." (PMID 34404439, 2021). "Epidermal growth factor receptor (EGFR) is frequently amplified or overexpressed in head and neck squamous cell carcinoma (HNSCC) and is a clinically validated target for the therapeutic antibody, cetuximab, in the management of this cancer." (PMID 33485341, 2021). "Epidermal growth factor receptor (EGFR) is frequently overexpressed in head and neck squamous cell carcinoma (HNSCC) and is a target for the therapeutic antibody cetuximab (CTX)." (PMID 35008337, 2021). "The EGFR-targeting antibody cetuximab (CTX) combined with radiotherapy has been proven effective for the treatment of locally advanced head and neck squamous cell carcinoma (LA-HNSCC)." (PMID 34207120, 2021). "Epidermal growth factor receptor (EGFR) remains the sole druggable molecular target other than the PD1/PD-L1 pathway with meaningful clinical benefit in squamous cell carcinoma of head and neck (SCCHN)." (PMID 34465724, 2021). "We previously found that inhibition of EGFR with cetuximab greatly improved the overall efficacy of RT in patients with head and neck squamous cell carcinoma (HNSCC)." (PMID 34830176, 2021). "IL-1α in combination with the EGFR inhibitor can induce a T cell-dependent anti-tumor immune response in head and neck squamous cell carcinomas." (PMID 34073987, 2021). "Cetuximab, an epidermal growth factor receptor inhibitor (EI), is currently the only targeted molecular therapy used in combination with radiotherapy for head and neck squamous cell carcinoma (HNSCC)." (PMID 33204681, 2020). "Intriguingly, despite the lack of a molecular pathway characterization, a recent study demonstrated the promising potential efficacy of two approved epidermal growth factor receptor (EGFR) inhibitors for FA-related head and neck squamous cell carcinoma." (PMID 32962238, 2020). "We used small inhibitory RNA (siRNA) to knockdown EGFR in 4 patient-derived head and neck squamous cell carcinoma (HNSCC) cell lines." (PMID 33106566, 2020). "Cetuximab, a monoclonal antibody against EGFR, is the only approved targeted therapy for head and neck squamous cell carcinoma (HNSCC)." (PMID 32731484, 2020). "Furthermore, the EGFR gene is amplified, overexpressed, or mutated in SCCs, such as head and neck squamous cell carcinoma (HNSCC)." (PMID 32546182, 2020). "Monoclonal anti-EGFR antibody Cetuximab (CTX) provides significant clinical benefit in patients with head and neck squamous cell carcinoma (HNSCC)." (PMID 32069320, 2020). "Cetuximab, an anti-EGFR monoclonal antibody (mAb), is approved for advanced head and neck squamous cell carcinoma (HNSCC) but benefits a minority." (PMID 32545260, 2020).
head and neck squamous cell carcinoma (continued). "Nonetheless, the on‐treatment biopsy from a patient with advanced head and neck squamous cell carcinoma showed a reduced INKA score and rank for EGFR as well as cell cycle‐associated kinases." (PMID 30979792, 2019). "EGFR is a member of receptor protein tyrosine kinase family with 42–80% over expression in head neck squamous cell carcinoma (HNSCC), whereas EGFR gene amplification is seen in up to 30% of HNSCC, and yet the results of EGFR targeting are not satisfactory." (PMID 31775759, 2019). "EGFR protein over-expression has been reported in 70 to 100% of head and neck squamous cell carcinomas (HNSCCs), and 46–72% of OPSCCs." (PMID 30630536, 2019). "Epidermal growth factor receptor (EGFR) overexpression is common in head and neck squamous cell carcinoma." (PMID 30700700, 2019). "The role of the epidermal growth factor receptor (EGFR) in the development and progression of head and neck squamous cell carcinoma (HNSCC) has been widely studied." (PMID 31165040, 2019). "The epidermal growth factor receptor (EGFR) is one of the most prominent oncogenes in head and neck squamous cell carcinoma (HNSCC)." (PMID 31537844, 2019). "Background: management of head and neck squamous cell carcinomas (HNSCC) include anti-Epidermal Growth Factor Receptor (EGFR) antibodies and radiotherapy, but resistance emerges in most patients." (PMID 31640284, 2019). "There is also more recent evidence that the soluble EpEx can sustain cell proliferation by acting as a ligand of EGFR in head and neck squamous cell carcinomas and colorectal cancers by inducing cell signalization through ERK1/2 and AKT." (PMID 31225512, 2019). "Trials on assessing the benefits of EGFR inhibitors in head and neck squamous cell carcinoma (HNSCC) patients have gradually been published." (PMID 31239839, 2019). "We also found overexpression of CD109 in other EGFR overexpressing head and neck squamous cell carcinoma cell line HN5." (PMID 29731998, 2018). "Here we studied if and how EGFR downstream signaling in head and neck squamous cell carcinoma (HNSCC) can affect the attraction of immune cells." (PMID 30192802, 2018). "A recent report stated that activation of epidermal growth factor receptor (EGFR)/Akt/mTOR axis acts as a positive feedback for constitutive upregulation of NF-κB subunit p65 in head and neck squamous cell carcinoma." (PMID 29381751, 2018). "For example, cetuximab, an anti-epidermal growth factor receptor (EGFR) antibody, is currently used as a sensitizer for radiation therapy in cases of head and neck squamous cell carcinoma." (PMID 30274183, 2018). "For loco-regional advanced head and neck squamous cell carcinoma, concomitant radiotherapy with anti-EGFR target therapy such as Cetuximab (C225, ErbituxTM) has been shown to improve locoregional control and reduce mortality." (PMID 28854970, 2017). "We previously demonstrated that API was able to selectively inhibit the tyrosine phosphorylation of specific residues of EGFR and ErbB2 in head and neck squamous cell carcinoma." (PMID 28674496, 2017). "When EGFR is overexpressed in head and neck squamous cell carcinoma (HNSCC), HER2 and HER3 are also expressed." (PMID 28939847, 2017). "Cetuximab, an anti-EGFR antibody, showed a survival benefit in patients with locoregionally advanced head and neck squamous cell carcinoma (HNSCC) when combined with RT." (PMID 28836950, 2017). "Cetuximab, the most commonly used anti-EGFR antibody, combined with radiotherapy (RT), has been shown to improve survival in patients with locoregionally advanced head and neck squamous cell carcinoma (LA HNSCC)." (PMID 29088889, 2017). "EGFR activation also promoted acquisition of CSC properties in head and neck squamous cell carcinoma and in nasopharyngeal carcinoma, pointing to a more general function of EGFR in CSC biology." (PMID 28148288, 2017).
head and neck squamous cell carcinoma (continued). "The epidermal growth factor receptor (EGFR) is one of the most comprehensively studied molecular targets in head and neck squamous cell carcinoma (HNSCC)." (PMID 29190900, 2017). "Since a majority of head and neck squamous cell carcinoma tumours express or overexpress epidermal growth factor receptor, the epidermal growth factor receptor inhibitors including cetuximab has been tried in these patients." (PMID 27841130, 2016). "Increased expression of epidermal growth factor receptor (EGFR) and its ligands is associated with poor prognosis and chemoresistance in many carcinoma types, but its role in head and neck squamous cell carcinoma (HNSCC) is unclear." (PMID 27669890, 2016). "EGFR has also been characterized as a critical factor in the development and progression of head and neck squamous cell carcinoma (HNSCC)." (PMID 26646588, 2016). "In head and neck squamous cell carcinoma, PS-1 positively modulates epidermal growth factor receptor (EGFR) expression independently of γ-secretase cleavage, whereas downregulation of PS-1 can inhibit the EGFR-STAT pathway." (PMID 26872378, 2016). "EGFR is expressed in 88–100% of head and neck squamous cell carcinomas, and is important in tumor cell growth, repair and survival." (PMID 25435943, 2015). "The epidermal growth factor receptor (EGFR) contributes to the pathogenesis of head&neck squamous cell carcinoma (HNSCC)." (PMID 25823819, 2015). "Cetuximab, an anti-EGFR antibody used for cancer therapy, was reported to be able to sensitize human head and neck squamous cell carcinoma cells to radiation in part through inhibiting radiation-induced upregulation of HIF-1α." (PMID 25997612, 2015). "A recent study reported that specific EGFR tyrosine kinase inhibitor erlotinib induce IL-6 expression in head and neck squamous cell carcinoma through NOX4/p38 and JNK/ NF-κB pathway." (PMID 26513016, 2015). "Increased expression of the epidermal growth factor receptor (EGFR) is observed in more than 90% of all head and neck squamous cell carcinomas (HNSCC)." (PMID 26032726, 2015). "Recently, Wu X. and colleagues published data suggesting that miR-27a* functions as a tumor suppressor in head and neck squamous cell carcinoma by targeting the EGFR signaling axis." (PMID 25749032, 2015). "B-type PACs isolated from grape seeds have been shown to target and downregulate EGFR expression in human head and neck squamous cell carcinoma (HNSCC) cells and inhibited their invasiveness." (PMID 25776829, 2015). "Cetuximab, a monoclonal antibody directed against the epidermal growth factor receptor (EGFR), is the only targeted therapy approved for treatment of squamous cell carcinoma of the head and neck (SCCHN)." (PMID 25081631, 2014). "The epidermal growth factor receptor (EGFR) is overexpressed in head and neck squamous cell carcinoma." (PMID 24722213, 2014). "A significant tumor specific overexpression of all four ErbB receptors including EGFR, ErbB2, ErbB3, and ErbB4 has been reported in head and neck squamous cell carcinomas (HNSCC)." (PMID 24886178, 2014). "The epidermal growth factor receptor (EGFR, ErbB-1) has been found to be expressed in virtually all head and neck squamous cell carcinomas." (PMID 25072020, 2014). "It has been reported that EGFR overexpression is a poor prognostic factor in head and neck squamous cell carcinoma." (PMID 25343854, 2014). "EGFR is highly expressed in a variety of epithelial tumors, such as non-small cell lung cancer, head and neck squamous cell carcinoma (HNSCC), colorectal cancer (CRC), and breast cancer." (PMID 23637996, 2013). "Overexpression of epidermal growth factor receptor (EGFR), as in our case, has been found in various epithelial malignancies, including head and neck squamous cell carcinoma (HNSCC), and is associated with increased tumor growth, metastasis, resistance to chemotherapeutic agents, and poor prognosis." (PMID 24222770, 2013).